FANCF (FA complementation group F)
Description:
DNA repair protein that may operate in a postreplication repair or a cell cycle checkpoint function. May be implicated in interstrand DNA cross-link repair and in the maintenance of normal chromosome stability (By similarity).
Synonyms: FAF
Tractability: PROTAC: ubiquitination databases record sites on it; a small molecule that binds it is known.
Target class: Other nuclear protein
Gene: Protein-coding gene on chromosome 11 (22,622,533 to 22,625,823, reverse strand). Ensembl gene ENSG00000183161.
Subcellular location: Nucleus
Subcellular location (Human Protein Atlas): Nucleoplasm
Pathways (Reactome):
DNA Repair: Fanconi Anemia Pathway
Immune System: PKR-mediated signaling
Gene Ontology:
Molecular function: protein binding
Biological process: DNA damage response; interstrand cross-link repair
Cellular component: chromatin; Fanconi anaemia nuclear complex; nucleoplasm; cytosol; nucleus
Genetic constraint (gnomAD): Missense variants: 552 observed, 520.8 expected, observed/expected ratio (o/e) 1.06, 90% interval 0.99 to 1.14. Synonymous variants: 257 observed, 221.44 expected, observed/expected ratio (o/e) 1.16, 90% interval 1.05 to 1.29.
Gene-disease validity (ClinGen):
ClinGen rates the evidence that FANCF causes each of these diseases.
Fanconi anemia complementation group F (autosomal recessive): Definitive.
Homologues: Orthologues: chimpanzee FANCF (98% identical), macaque FANCF (94% identical), pig FANCF (73% identical), rabbit FANCF (71% identical), guinea pig FANCF (59% identical), rat Fancf (50% identical), mouse Fancf (46% identical), dog FANCF (46% identical), zebrafish fancf (25% identical), tropical clawed frog fancf (24% identical).
Diseases named in the same sentence as FANCF in open-access papers:
FANCF is named in the same sentence as 40 diseases in open-access papers, as found by Europe PMC text mining. Sharing a sentence is not in itself a finding about the gene and the disease. The quoted sentences say what the papers report.
Fanconi anemia (28 papers, 2012 to 2025). Fanconi anemia (FA) is a hereditary DNA repair disorder characterized by progressive pancytopenia with bone marrow failure, variable congenital malformations and predisposition to develop hematological or solid tumors. "The mutation in the FANCF gene (FANCF_A81V), encoding the DNA repair protein Fanconi Anemia Complementation group F, is identified in a PDTC (HD97 patient)." (PMID 37867524, 2023). "FANCF (Fanconi anemia, complementation group M) is a gene associated with Fanconi anemia, the protein products of which were reported to interact with proteins involved in DNA repair pathways, e.g., with BRCA1." (PMID 35582723, 2019). "More than 15 years ago, Olopade and Wei described a model of ovarian cancer tumor progression that implicated aberrant FANCF promoter methylation and correlated with gene silencing and disruption of the Fanconi-anemia-BRCA pathway." (PMID 35582723, 2019). "This last region is of interest as it encloses the FANCF gene, involved in the Fanconi anemia pathway and commonly associated to squamous cell carcinoma susceptibility." (PMID 29377909, 2018). "It is the first report of a mutation in the FANCF gene in Iranian patients with Fanconi anemia." (PMID 31288759, 2019). "In the present study, we downregulated FANCF expression by small interfering RNA (siRNA) in OVCAR ovarian cancer cells to address the effects of decreased FANCF expression on the function of the Fanconi anemia (FA)/breast cancer susceptibility gene (BRCA) pathway." (PMID 23440494, 2013). "FANCF (Fanconi anemia complementation group F) participants in the development of Fanconi anemia, a study of the serum of idiopathic PD (IPD) patients found lower levels of FANCF in the IPD group." (PMID 41026459, 2025). "FANCF is an adaptor protein of the Fanconi Anemia core complex and plays a key role in DNA post-replication repair and in cell-cycle checkpoints." (PMID 37867524, 2023). "Promoter regions of some genes were shown to be methylated in epithelial ovarian cancers, such as Fanconi anemia complementation group F (FANCF) and RASSF2A genes." (PMID 29156803, 2017). "‘BRCAness’ and PARP inhibitor sensitivity has also been observed in cells exhibiting promoter methylation of the of the Fanconi Anemia FANCF gene." (PMID 25026298, 2014). "Moreover, 14% of the patients included in this study harbored deleterious mutations in Fanconi anemia genes (FANCA, FANCD2, FANCF, FANCG FANCI and FANCL) and in WRN, which have been reported to interact with BRCA1." (PMID 38184614, 2024). "Besides ABCC4, POLE3, POLE4, and the Fanconi anemia pathway genes FANCF and C17orf70 are top candidates that sensitize both wild-type and TDP1-KO cells to CPT treatment." (PMID 35869071, 2022). "FANCF, known as Fanconi anemia complementation group F, are essential in DNA repair." (PMID 31781476, 2019). "Deleterious alterations were also identified in nearly all (13/14) tumours in members of the Fanconi anaemia complementation groups, including FANCD2, FANCF, FANCC, FANCA, and FANCE." (PMID 34045664, 2022). "The three Fanconi anemia genes FANCC, FANCF, and FANCL were identified as candidate autophagy factors via whole genome screening." (PMID 33575215, 2020). "The Fanconi anemia pathway genes FANCB, POLN, DCLRE1A, UBA52, and FANCF genes were significantly (p < 0.01, T-test) downregulated after radiation only in FANCA-deficient HIO lines." (PMID 32085439, 2020). "In line with this key observation, FANCF, another member of the BRCA1/Fanconi anemia pathway, was also hypermethylated." (PMID 30683142, 2019). "Relevant to the adaptation of TRD to arid conditions, ten selected genes (including SLX4, FANCF, FANCG, FANCI, ATR, and POLH) were related to the fanconi anemia pathway (bta03460, p < 0.01) involved in DNA repair, DNA replication fork stability, and other cellular processes." (PMID 33072165, 2020).
Fanconi anemia (continued). "Additionally, we found 7 monoallelic pathogenic variants (2%, 7/327) in 6 genes (besides BRCA1/2) of the interstrand crosslink DNA repair Fanconi anemia pathway (FANCB, FANCC, FANCF, FANCI, FANCL, FANCM) and 1 in RAD51C, a Fanconi-like phenotype gene." (PMID 30262796, 2018). "Moreover, we speculate that both proteins are likely to function in the Fanconi Anemia pathway as knockdown of Snm1B does not increase the sensitivity of FANCD2-deficient cells to MMC, and PSF2 interacts with the FANCF protein." (PMID 23189151, 2012).
ovarian carcinoma (23 papers, 2008 to 2024). A malignant neoplasm originating from the surface ovarian epithelium. "Methylation of the FANCF promoter in ovarian cancer has been linked to platinum sensitivity, whereas demethylation of FANCF has been associated with platinum resistance and often occurs after platinum chemotherapy." (PMID 35326684, 2022). "FANCF deficiency has been linked to development of ovarian cancer in vivo, and methylation has been observed as a mechanism of suppression in patient samples." (PMID 36046263, 2020). "The 2008 ovarian carcinoma line is deficient in FA pathway function due to methylation of the FANCF promoter region." (PMID 19371427, 2009). "Moreover, FANCF promoter methylation has been found in cancer and a FANCF-deficient mouse model was prone to ovarian cancers." (PMID 37867524, 2023). "Although it has been reported that the TOV-21G cells absent of FANCF function with FANCF cDNA are resistant to MMC and CDDP, our study is the first to investigate the sensitivity of OVCAR3 ovarian cancer cells to another therapeutic drug ADM through loss of function of FANCF." (PMID 23440494, 2013). "Ovarian cancer cell lines were therefore used to investigate whether FANCF methylation is associated with cisplatin sensitivity, and these cisplatin-sensitive cells exhibited a densely methylated promoter region of the FANCF gene, which was accompanied by a lack of FANCF mRNA expression." (PMID 38256203, 2024). "To test this hypothesis, we performed isobologram analyses on the ovarian cancer cell line 2008, which is deficient in the FA pathway due to hypermethylation of the FANCF promoter, and on its isogenic, complemented FA pathway-proficient counterpart 2008 + FANCF cell line." (PMID 22537224, 2012). "In the next models of mouse xenografts with FANCF-deficient and proficient ovarian cancer cell lines, the group observed NVB effectiveness especially on FANCF-deficient tumors when the vehicle had an impact on any of the cases." (PMID 36613762, 2022). "Ovarian cancer cells can restore this pathway through demethylation and derepression of FANCF, resulting in acquired cisplatin resistance." (PMID 35682605, 2022). "This divergence is reconciled under a model of biphasic requirement of the FA pathway throughout the initiation and progression of cancer, reminiscent of stage-specific alteration of FANCF expression by promoter methylation in ovarian cancer." (PMID 32190289, 2020). "FANCF has been demonstrated to be supressed by gene hypermethylation in ovarian cancer, leading to a chemosensitive phenotype which is reversed by demethylation during the development of chemoresistance." (PMID 36046263, 2020). "A subset of ovarian cancer cell lines with FANCF methylation are hyper-sensitive to cisplatin while FANCF complementation in these cells restores resistance." (PMID 32190289, 2020). "Epigenetic silencing of FANCF, such as methylation-induced inactivation of FANCF, plays an important role in the occurrence of several types of cancer including ovarian cancer via disruption of the FA/BRCA pathway." (PMID 23440494, 2013). "Here, we downregulated expression of FANCF by siRNA in an OVCAR ovarian cancer cell line and evaluated the effects of decreased FANCF expression on the function of the FA/BRCA pathway in OVCAR cells and their chemosensitivity to ADM." (PMID 23440494, 2013). "In conclusion, our findings demonstrated that FANCF silencing-induced dysfunction of the FA/BRCA pathway increased the sensitivity of the human ovarian cancer cell line, OVCAR, to ADM, by increased cell apoptosis dependent on JNK activation." (PMID 23440494, 2013). "Fifteen of these 43 compounds were then confirmed to inhibit IR-induced FANCD2 foci formation in multiple cell lines, including PD20-FANCD2, U2OS, HeLa and TOV21G + FANCF ovarian cancer cells, using a wide range of drug concentrations (and data not shown)." (PMID 22537224, 2012).
ovarian carcinoma (continued). "Promoter methylation leads to decreased expression of BRCA1, MLH1, and FANCF protein in a subset of ovarian carcinomas." (PMID 19602291, 2009). "These authors found no mutation in the FANCF gene, but methylation of the promoter region of FANCF in 4 out of 19 (21%) ovarian cancer samples." (PMID 18414472, 2008). "This study confirmed methylation-dependent silencing of FANCF in one out of nine ovarian cancer cell lines." (PMID 18414472, 2008). "Promoter methylation was assessed by methylation-sensitive polymerase chain reaction of FANCF in nine ovarian cancer cell lines and 74 ovarian cancer samples taken from patients entered on a trial of cisplatin-based chemotherapy." (PMID 18414472, 2008). "Observations in tissues of primary ovarian cancer revealed that the FA gene FANCF was methylated in 21% of the tissues examined, and it was hypothesized that the disruption of the FA/BRCA pathway might contribute to the initial sensitivity toward cisplatin." (PMID 38256203, 2024). "Monoubiquitination of FANCD2 is a measure of the activity of this DNA damage repair pathway, and disruption of this pathway in ovarian cancer results from the hypermethylation and silencing of one of the FA genes, FANCF, leading to increased sensitivity to the DNA-damaging agent cisplatin." (PMID 35682605, 2022). "Furthermore, hypermethylation of other DNA damage repair pathway-related genes, like GSTP1, FANCF, and MGMT, has been described to be positively associated with chemosensitivity in ovarian cancer patients." (PMID 28641578, 2017). "In the present study, we silenced the FANCF gene by RNA interference in OVCAR3 ovarian cancer cells and found decreased expression of FANCF protein, ratio of FANCD2-L/FANCD2-S and FANCD2 foci, which suggests inactivation of the FA/BRCA pathway by FANCF silencing in OVCAR3 ovarian cancer cells." (PMID 23440494, 2013). "In the present study, shRNA was used to knockdown FANCF expression in OVCAR3 ovarian cancer cells." (PMID 23440494, 2013). "We propose that FANCF may represent a novel target for enhancing the response of ovarian cancer cells to ADM, thus improving ovarian cancer treatment." (PMID 23440494, 2013). "We also found that FANCF silencing increased the sensitivity of OVCAR3 ovarian cancer cells to ADM." (PMID 23440494, 2013). "In this study, we have addressed the hypothesis that methylation-dependent transcriptional silencing of FANCF is a determinant of clinical response and outcome to platinum-based adjuvant chemotherapy of epithelial ovarian cancer." (PMID 18414472, 2008). "We analysed methylation in the FANCF CpG island in a panel of ovarian cancer cell lines." (PMID 18414472, 2008). "Thus, interference of FANCF expression may be a new approach to improve chemosensitivity in the treatment for ovarian cancer." (PMID 23440494, 2013). "Six small molecules, including bortezomib (proteasome inhibitor), CA-074-Me (cathepsin B inhibitor) and 17-AAG (HSP90 inhibitor), synergized with cisplatin specifically in FA-proficient ovarian cancer cells (2008 + FANCF), but not in FA-deficient isogenic cells (2008)." (PMID 22537224, 2012). "In fact, epigenetic silencing of FANCF via promoter methylation and reduced levels of FANCD2 have been previously detected in ovarian cancer." (PMID 22253870, 2012). "Promoter hypermethylation of FANCF is observed in cases of AML and ovarian cancer." (PMID 28239445, 2017). "Collectively, we confirm that silencing of FANCF sensitizes OVCAR3 ovarian cancer cells to ADM, suggesting that FANCF may serve as a potential target for therapeutic strategies in the treatment of ovarian cancer." (PMID 23440494, 2013). "Alteration in methylation of the promoters of BRCA1, MLH1, and FANCF do not seem to commonly mediate clinical chemoresistance in women with ovarian carcinomas." (PMID 19602291, 2009). "This study does not support methylation-dependent silencing of FANCF as a mechanism of sensitisation to platinum-based chemotherapy in ovarian cancer." (PMID 18414472, 2008).
ovarian carcinoma (continued). "However, our findings indicate that FANCF methylation occurs rarely in primary ovarian carcinomas (<5% of cases), and is therefore not likely to be a major clinical mediator of platinum sensitivity." (PMID 19602291, 2009). "Furthermore, methylation of FANCF is unlikely to have a major impact on response to established anticancer agents in epithelial ovarian cancer." (PMID 18414472, 2008). "It is therefore likely that FANCF methylation is not a major feature of chemonaive ovarian cancers, but may be a ‘progression factor’ occurring late in the process of carcinogenesis." (PMID 18414472, 2008).
breast carcinoma (9 papers, 2012 to 2023). "High expression of FA genes (FANCF D1/D2/I/J/N/S) has been demonstrated linked to poor prognosis in various cancers, including head and neck cancer, myeloid leukemia, liver cancer, lung cancer, breast cancer, cervical cancer, and ovarian cancer." (PMID 36685883, 2022). "When the concentration of ADR is large or the treatment time is longer, the expression of REV1 and FANCF is decreased in breast cancer cells." (PMID 31511498, 2019). "MAP kinases, JNK and p38, are activated when the FA/BRCA pathway is inhibited by gene silencing of FANCF in breast cancer cells." (PMID 24124520, 2013). "This is the first study to report on RNAi-mediated FANCF silencing-induced dysfunction of the FA/BRCA pathway in breast cancers." (PMID 22952942, 2012). "In this study, we examined the effects and mechanisms of FANCF-RNAi on the sensitivity of breast cancer cells to mitoxantrone (MX)." (PMID 22952942, 2012). "We also found that FANCF silencing potentiated the sensitivity to MX in breast cancer cells, accompanying with an increase in intracellular MX accumulation and a decrease in BCRP expression." (PMID 22952942, 2012). "Compared with the control, FANCF shRNA significantly enhanced the MX-induced decrease in the cell viability in both cell lines (P<0.05), suggesting that known-down of FANCF significantly potentiated the cytotoxic effects of MX on breast cancers." (PMID 22952942, 2012). "Our study also shows that FANCF silencing sensitizes breast cancer cells to MX, the topoisomerase II poison-MX." (PMID 22952942, 2012). "In this study, we find that knockdown of FANCF potentiates the sensitivity of breast cancer cells to MX." (PMID 22952942, 2012). "FANCF silencing by FANCF-shRNA blocked functions of FA/BRCA pathway through inhibition of FANCD2 mono-ubiquitination in breast cancer cell lines MCF-7 and T-47D." (PMID 22952942, 2012). "Studies have shown that down-regulation of FANCF expression can inhibit the proliferation, migration and invasion of breast cancer cells, which may be related to hypermethylation of its promoter." (PMID 37845668, 2023). "We next examined the effects of FANCF silencing on MX accumulation in breast cancer cells." (PMID 22952942, 2012). "Therefore, we examined changes in the expression of proteins association with the MAPK pathway, including JNK, ERK, and p38 in breast cancer cells following FANCF gene silencing." (PMID 22952942, 2012). "In addition, FANCF shRNA inhibited cell proliferation, induced apoptosis, and chromosome fragmentation in both breast cancer cells." (PMID 22952942, 2012). "Although our studies have demonstrated that FANCF silencing significantly increases MX sensitivity in vitro, it is critical to further define the role of FANCF in regulating MX sensitivity of breast cancer in vivo to evaluate the clinical significance of FANCF." (PMID 22952942, 2012). "Our findings indicate that FANCF shRNA potentiates the sensitivity of breast cancer cells to MX, suggesting that FANCF may be a potential target for therapeutic strategies for the treatment of breast tumors." (PMID 22952942, 2012).